OVAAL (ovarian adenocarcinoma amplified long non-coding RNA)
Synonyms: LINC01131; OVAL; RMEL2
Gene: Long non-coding RNA gene on chromosome 1 (180,509,380 to 180,566,523, forward strand). Ensembl gene ENSG00000236719.
Gene Ontology:
Molecular function: pre-mRNA branch point binding
Biological process: mRNA branch site recognition
Cellular component: U2 snRNP
Diseases named in the same sentence as OVAAL in open-access papers:
OVAAL is named in the same sentence as 13 diseases in open-access papers, as found by Europe PMC text mining. Sharing a sentence is not in itself a finding about the gene and the disease. The quoted sentences say what the papers report.
melanoma (3 papers, 2010 to 2021). A malignant, usually aggressive tumor composed of atypical, neoplastic melanocytes. "In melanoma, several lncRNAs were recently reported to be associated with the initiation and progression of melanoma, such as SPRY4-IT1, Llme23, OVAAL, SRA, and LINC00520." (PMID 33311650, 2021). "A study has found that OVVAL is highly expressed in colon cancer and melanoma, and further experimental results showed that OVAAL promotes the proliferation of cancer cells via dual mechanisms controlling RAF/MEK/ERK signaling and p27-mediated cell senescence." (PMID 33614260, 2021).
cancer (5 papers, 2010 to 2023). A tumor composed of atypical neoplastic, often pleomorphic cells that invade other tissues. "OVAAL, has been previously identified to play a significant role in cell survival, proliferation, and evasion from cellular senescence and contributes to cancer cell survival." (PMID 34691143, 2021).
Cardiovascular disease (1 paper, 2024). "Among these, 10 regions, proximal to or within the genes OVAAL, BMP3, RIOK1, AC096553.5, MCPH1, KCNU1, GLIS3, TUT7, TRIB3, and SYNDIG1, represent novel associations with MI and have not been previously linked to Cardiovascular disease (CVD)-related traits." (PMID 38725839, 2024).
OVAAL also shares sentences with these, for which no sentence is quoted: colon cancer (2 papers); endometrial cancer (2); breast carcinoma (1); colorectal cancer (1); gastric cancer (1); glioblastoma (1); lung adenocarcinoma (1); multiple myeloma (1); ovarian carcinoma (1); tumor (1).